ACOD1 (aconitate decarboxylase 1)
Diseases named in the same sentence as ACOD1 in open-access papers (continued):
Sharing a sentence is not in itself a finding about the gene and the disease.
tumor (continued). "Acod1 is a potential target for therapy to prevent tumor metastasis, and inhibition of Acod1 may promote the ferroptosis sensitivity of immunosuppressive TINs and reduce tumor metastasis." (PMID 39273650, 2024). "Tumor‐secreted GM‐CSF induces ACOD1 expression in neutrophils through the STAT5‐C/EBPβ axis." (PMID 39492834, 2024). "Importantly, the combination of low-dose anti-CD47 antibody with ACOD1-/- MSLN-iMACs had the most superior tumor suppression effect." (PMID 37723178, 2023). "In vitro tumor killing capacity was enhanced in ACOD1-/- MSLN-CAR-iMACs which could be reversed by supplementing 4-OI." (PMID 37723178, 2023). "Finally, the luciferase assay showed ACOD1-/- iMACs had higher cytolytic activity against tumor cells." (PMID 37723178, 2023). "Following the discrimination of microglia from monocyte‐derived macrophages and the characterization of their transcriptional programmes along tumour progression, we assess the role of aconitate decarboxylase 1/immunoresponsive gene 1 (Acod1/Irg1) in TAM polarization." (PMID 35838338, 2022). "The tumor cells educated tissue-resident macrophages via some unknown mechanisms and dramatically elevated the expression of Acod1 and, consequently, the itaconate level as well." (PMID 32724492, 2020). "Itaconate, a metabolite produced primarily by activated macrophages catalyzed by ACOD1, can be taken up by tumor cells via the SLC13A3 transporter, thereby activating the NRF2-SLC7A11 pathway and protecting tumor cells from iron death." (PMID 41226585, 2025). "ACOD1-depletion effectively facilitated CAR-iMAC polarization towards the M1 phenotype, resulting in enhanced antitumor activities both in vitro and in vivo including tumor suppression and stronger phagocytosis compared to CAR-iMACs with intact ACOD1." (PMID 40376682, 2025). "Itaconate, a TCA cycle–derived immunometabolite produced by aconitate decarboxylase 1 (ACOD1/IRG1), has diverse roles in inflammation, microbial defense, and tumor biology." (PMID 40931345, 2025). "Tumor-infiltrating neutrophils (TIN) exhibit resistance to ferroptosis, potentially through the upregulation of aconitate decarboxylase 1 (Acod1), which produces itaconates and activates the Nrf2 pathway." (PMID 40285867, 2025). "Activation of ACOD1 reduces TIN ferroptosis by generating itaconate and activating Nrf2‐mediated antioxidant response, thereby sustaining the abundance of TINs in tumor metastasis." (PMID 39492834, 2024). "Acod1-/- mice exhibited enhanced CD8+ T cell responses towards transplanted tumors, decreased MDSC accumulation and reduced tumor growth." (PMID 38487538, 2024). "Tumour volume measurement by MRI for biopsy collection at early, intermediate and late stage in GL261 tumour‐bearing WT and Acod1 KO mice used for scRNA‐seq analyses (1 mouse per condition)." (PMID 35838338, 2022). "Mechanistically, tumor cells induce Irg1 expression in macrophages by activating NF-κB pathway, and ITA produced by ACOD1 inhibits TET DNA dioxygenases to dampen the expression of inflammatory genes and the infiltration of CD8+ T cells into tumor sites." (PMID 37115931, 2023). "In addition, combining ACOD1-depleted CAR-iMACs with immune checkpoint inhibitors (ICI), such as anti-CD47 or anti-PD1 antibodies, result in even stronger tumor suppressing effect." (PMID 37723178, 2023). "Thus, ACOD1 is a fresh metabolic target to engineer CAR-iMACs, in order to elevate their anti-tumor function and to eliminate tumor cells." (PMID 37723178, 2023). "ACOD1-/- MSLN-CAR-iMACs exhibited enhanced M1-like polarization and stronger anti-tumor activity." (PMID 37723178, 2023). "In addition, small sample size did not allow for correlation of ACOD1 and itaconate levels with tumor stage." (PMID 40552282, 2025). "Moreover, ACOD1 depleted iMACs or CAR-iMACs are superior in comparison to the unmodified ones in cancer immunotherapies because of their enhanced in vitro and in vivo anti-tumor functions." (PMID 37723178, 2023).
tumor (continued). "This study thus lays down the proof of principle for targeting ACOD1 in myeloid cells for cancer immunotherapy and introduces metabolically engineered human iPSC-derived CAR-iMACs cells with enhanced polarization and anti-tumor functions in adoptive cell transfer therapies." (PMID 37723178, 2023).
cancer (23 papers, 2017 to 2025). A tumor composed of atypical neoplastic, often pleomorphic cells that invade other tissues. "One may hypothesize that the change to Met154 in human ACOD1, reducing itaconic acid synthesis, could contribute to a higher resistance against cancer, whereas the frequent Asn152Lys variant counteracts this reduction of enzyme activity, potentially improving host defence against infections." (PMID 37365251, 2023). "In addition, considering the protumorigenic effects of ACOD1, citraconate may prove useful as a scaffold for the development of ACOD1 inhibitors for cancer therapy." (PMID 35655026, 2022). "This occurs particularly through aconitate decarboxylase 1 (ACOD1)‐driven itaconate production, which inflicts DNA damage on neighboring cancer cells." (PMID 40904700, 2025). "Furthermore, TAM‐derived itaconate, generated when ACOD1 diverts the TCA cycle, promotes cancer cell mutagenesis through ROS‐dependent DNA damage." (PMID 40904700, 2025).
bacterial infection (14 papers, 2014 to 2025). "Regardless, the STING1-MYD88 complex plays a major role in mediating ACOD1 expression during bacterial infection, especially in response to TLR1/2/4/5/6 signals." (PMID 35769880, 2022).
infectious disease (5 papers, 2016 to 2024). A disorder directly resulting from the presence and activity of a microbial, viral, or parasitic agent in humans. "We also cannot rule out whether the MYD88-STING1 pathway is required for ACOD1-related inflammatory responses in other infectious diseases or tissue damage." (PMID 35769880, 2022).
metabolic disease (2 papers, 2023 to 2024). A congenital disorder (due to inherited enzyme abnormality) or acquired (due to failure of a metabolically important organ) disorder resulting from an abnormal metabolic process. "By using multiomics-integrated approaches, here we show that ACOD1 responds to high-fat diet consumption in mice by promoting gut microbiota alterations supporting metabolic disease." (PMID 38302438, 2024). "Importantly, such effects were abrogated by oral administration of low dose of itaconate (1 mM) to HFD-fed Acod1-/- mice, indicating an instrumental role for itaconate production in development of metabolic disease." (PMID 38302438, 2024). "To determine whether Acod1 is responsive to fat overnutrition, we challenged five-week old wild type mice with standardized high-fat diet (HFD) containing 60% of calories from fat for 16 weeks to promote metabolic disease." (PMID 38302438, 2024).
neurodegenerative disease (2 papers, 2024 to 2025). A disorder of the central nervous system characterized by gradual and progressive loss of neural tissue and neurologic function. "Although research on the ACOD1 protein is still in its early stages, further understanding of the ACOD1/itaconate pathway in neurodegeneration might identify a new molecular target for inhibiting neuroinflammation, a common characteristic of neurodegenerative diseases such as AD and PD." (PMID 39334733, 2024).
ACOD1 also shares sentences with these, for which no sentence is quoted: inflammation (5 papers); Salmonella Infections (5); idiopathic pulmonary fibrosis (4); autoimmune disease (3); melanoma (3); pulmonary disease (3); Zika virus infection (3); cardiovascular disease (2); colon cancer (2); dyslipidemia (2); glioblastoma (2); hepatocellular carcinoma (2); inflammatory bowel disease (2); lung carcinoma (2); psoriasis (2); acute lymphocytic leukemia (1); allergic asthma (1); Allergy (1); anemia (1); animal disease (1); Autoimmunity (1); brain injury (1); carditis (1); cerebral infarct (1); chorioamnionitis (1); clostridium difficile infection (1); colon adenocarcinoma (1); cystic fibrosis (1); Depression (1); end-stage renal disease (1).
A further 34 diseases each share a sentence with ACOD1 in 1 paper.